PCBP1 (poly(rC) binding protein 1)
Diseases named in the same sentence as PCBP1 in open-access papers (continued):
Sharing a sentence is not in itself a finding about the gene and the disease.
cancer (43 papers, 2010 to 2025). A tumor composed of atypical neoplastic, often pleomorphic cells that invade other tissues. "Experimental data describe the regulation of transcriptional activation at the LIFR promoter locus and indicate that the loss of PCBP1 expression induces FAM3C/LIFR-driven signaling that regulates transcriptional events associated with carcinoma pathology." (PMID 37927213, 2023). "We apply easyCLIP to the 33 most recurrent cancer mutations across 28 RBPs, finding increased RNA binding per RBP molecule for KHDRBS2 R168C, A1CF E34K and PCBP1 L100P/Q cancer mutations." (PMID 33692367, 2021). "To further explore the impacts of mutant RBPs in cancer, we analyzed the transcriptomic effects of recurrent missense mutations in PCBP1 and KHDRBS2." (PMID 33692367, 2021). "Depletion of PCBP1 is implicated in various carcinomas, but the underlying mechanism in tumorigenesis remains elusive." (PMID 30086790, 2018). "Importantly, two leucine residues (Leu100 and Leu102) of PCBP1 protein are frequently mutated in cancers and are essential for PCBP1 function." (PMID 36505770, 2022). "PCBP1 could be used as a diagnostic marker to cancer patients." (PMID 30086790, 2018). "PCBP1 is ubiquitously expressed at high levels in mammalian cells, as it is necessary for iron chaperone activity, and PCBP1 protein is indeed abundant in untreated cancer cell lines." (PMID 40362430, 2025). "Iron homeostasis dynamics in cancer, intracellular localization of reactive iron, and the impact of PCBP1 on intracellular iron handling, are important areas of further research to enable the translation of ferroptosis therapeutic strategies." (PMID 40362430, 2025). "PCBP1, which is considered to be a tumor suppressor in various types of cancer, regulates gene expression in multiple ways, including transcription, alternative splicing, and translation." (PMID 39170746, 2024). "In turn, overexpression of miR-490-3p, by stimulating ERGIC3 and inhibiting PCBP1, promotes the proliferation and migration of cancer cells and disturbs the body’s natural immune response, taking part in the development of many cancers, including MM." (PMID 38473390, 2024). "Depletion of PCBP1 is associated with EMT, tumor progression, increased metastatic potential, and increased cancer cell stemness." (PMID 39342995, 2024). "PCBP2, highly homologous to its family member PCBP1, is expressed in many cancers and is considered an oncogene that promotes tumorigenesis." (PMID 36452487, 2022). "And cell spreading, more specifically, the migration and metastasis of cancer cells was found stimulated when PCBP1 was inhibited." (PMID 35100974, 2022). "PCBP1 has been identified as regulating alternative splicing, translation, and RNA stability of many cancer-related genes." (PMID 35907982, 2022). "Upregulated PCBP1 led to significant upregulation of TPM3 in cancer tissues by directly binding to TPM3 mRNA and enhancing its mRNA stability, promoting migration and invasion of ESCC cells." (PMID 35287546, 2022). "It is evident from the studies on autoinflammatory diseases and cancers that PCBP1 participates in the regulation of immune response." (PMID 35589811, 2022). "PCBP1 can promote the production of GM-CSF in T cells, PCBP1 is an intracellular immune checkpoint for shaping T-cell responses in cancer immunity, and PCBP1 modulates the innate immune response." (PMID 35907982, 2022). "Poly (rC)-binding protein (PCBP1) belongs to the heterogeneous nuclear ribonucleoprotein (hnRNP) family, and downregulation of PCBP1 has been observed in a variety of cancers." (PMID 36210846, 2022). "Simultaneously, better outcome of patients with certain cancers was reported in the presence of PCBP1 overexpression." (PMID 35100974, 2022). "It has been reported that PCBP1 is relevant to tumorigenesis in diverse human cancers, and circadian clocks have close interactions with cancer metabolism." (PMID 33841513, 2021).
cancer (continued). "In reverse, PCBP1 is involved in several cellular processes that, in particular, are related to iron metabolism and it is largely studied in cancer." (PMID 33804639, 2021). "In three cases, recurrent cancer-associated missense mutations in RBPs increased binding to RNA: KHDRBS2, A1CF, and PCBP1." (PMID 33692367, 2021). "A total of 12 splicing factors were significantly associated with the OS of KIRC, among which splicing factors such as PCBP1, hnRNPK and hnRNPM were engaged in tumorigenesis through guiding alternative splicing programs in various cancers 31-33." (PMID 32047561, 2020). "Meaningfully, PCBP1 is reported to participate in EMT pathways in cancer, especially in the TGF-β pathway." (PMID 32552766, 2020). "This, for instance, highlighted the Poly(rC) binding protein 1 (PCBP1) as a possible cancer gene candidate." (PMID 29572294, 2018). "Recent studies indicate that PCBP1 phosphorylation at Ser43 by Akt2 upon TGF-beta stimulation promotes epithelial to mesenchymal transition in various cancer cells." (PMID 30086790, 2018). "Among the enriched transcripts, p27 mRNA is a novel PCBP1-bound transcript related to cell cycle proliferation, whose abnormal expression is putatively described in many types of cancers." (PMID 30086790, 2018). "Immunohistochemistry showed that lower expression of PCBP1 and p27 were synchronously observed in both ovary and colon carcinomas." (PMID 30086790, 2018). "Future studies are needed to characterize the interaction between PCBP1 and Akt, and their contribution to drug resistance in cancer therapy." (PMID 28076324, 2017). "PCBP1 expression levels in tumors may serve as predictors for prognostic assessment and response to cancer therapy involving ferroptosis inducers." (PMID 39845670, 2024). "Our work contributes to the multifaceted roles of PCBP1 and its importance in cancer biology." (PMID 39342995, 2024). "We also explored the role of PCBP1 in cancer metastasis in LUAD." (PMID 35907982, 2022). "PolyC-RNA-binding protein 1 (PCBP1) is also known as hnRNP E1, which was identified as a component of heterogeneous nuclear ribonucleoprotein complexes and regulates alternative splicing, translation, and RNA stability of many cancer-related genes." (PMID 35907982, 2022). "Furthermore, PCBP1 expression was significantly reduced in stage IV cancer tissues corresponding to patients with distant metastasis." (PMID 35907982, 2022). "All these findings highlight the clinical significance of PCBP1 in cancers." (PMID 35907982, 2022). "Recent studies indicated that the process of EMT existing in a variety of cancer cells could be triggered by the phosphorylation of PCBP1 at Ser43 by Akt2 upon TGF-β stimulation." (PMID 35100974, 2022). "PCBP1 protein is often downregulated in cancer, which aids in tumorigenesis." (PMID 33692367, 2021). "Overall, our results provide a potential concept that autophagy inhibition could be an efficient strategy to induce malignant tumors to undergo apoptotic cell death, when PCBP1 depletion." (PMID 32922440, 2020). "PCBP1 is as yet not classified as a driver, but it is involved in the regulation of the expression of a number of cancer genes and has been previously implicated in tumorigenesis and metastasis." (PMID 29572294, 2018). "All these highlight the clinical significance of PCBP1 in cancers." (PMID 30086790, 2018). "This study pioneers the discovery of a small molecule inhibitor that targets both PCBP1/2 and GPX4, offering a novel therapeutic strategy for eliminating cancer cells through ferroptosis." (PMID 40619432, 2025). "PCBP1 is a multifunctional RBP that regulates the alternative splicing, translation, and RNA stability of many cancer-related genes to exert its cancer-inhibiting effect." (PMID 36289466, 2022). "For example, the PCBP1, SRSF3, and NIFK promotes cancer progression in metastasis or carcinogenesis." (PMID 32219019, 2020).
cancer (continued). "Expression of other members of RQC including Pelota, SMG1 did not correlate across cancer types, nor were patterns observed in the expression of reference genes (GAPDH, HNRPL, PCBP1, SNW1, and RER1) identified to have stable expression patterns in human cancer and matching normal cell types." (PMID 38140537, 2023). "Additionally, PCBP1 inhibits the expression of STAT3, an oncogene frequently overexpressed in cancer, through the interaction with its 5’-UTR." (PMID 36452487, 2022). "Given above results and the promoting-role of CD44v6 in EMT in cancers, we further studied that whether circ0003998 promoted the EMT of HCC by protecting the CD44v6 from down regulation by PCBP1." (PMID 32552766, 2020). "Furthermore, two‐thirds of the identified instances were not classified as known cancer genes but many could be functionally linked to cancer pathways or were, as exemplified by Poly(rC) binding protein 1 (PCBP1), previously suggested to have a role in the regulation of cancer genes and proteins." (PMID 29572294, 2018).
infection (7 papers, 2011 to 2024). The state of being infected such as from the introduction of a foreign agent such as serum, vaccine, antigenic substance or organism. "Since PCBP1 abundance was decreased with simultaneous appearance of a faster moving band, we assumed that PCBP1 was cleaved because of LD infection." (PMID 36309090, 2022). "Beyond its interactions with the 5′ UTR, previous reports suggested that PCBP1 was not necessary for HCV IRES-mediated translation, but that knockdown of PCBP1 decreases HCV RNA accumulation during infection." (PMID 35215884, 2022). "In agreement with our previous findings, we observed an overall reduction in JFH-1T viral RNA accumulation by day 3 post-infection during PCBP1 knockdown (0 h timepoint)." (PMID 35215884, 2022). "Intact PCBP1 band became almost undetectable within 30 min of infection in J774 cells, whereas intact PCBP2 level was decreased steadily with increasing time of infection as detected in Western blots." (PMID 36309090, 2022). "In EV71-infected cells, EV71 replication (indicated as dsRNA) was occurred in the cytoplasm at 6 h and 12 h post-infection, while PCBP1 protein was mainly distributed in the cytoplasm." (PMID 24489926, 2014). "In EV71-infected cells, EV71 3C protein was expressed and mainly distributed in the cytoplasm at 6 h and 12 h post-infection, while majority of PCBP1 in the cytoplasm of EV71-infected cells and co-localized with EV71 3C protein." (PMID 24489926, 2014). "In addition, the level of EV71 VP1 protein was increased as the infection time increased (lanes 3, 5, and 7), but further enhanced by over-expression of PCBP1 (lanes 4, 6, and 8) and reduced by knocked-down of PCBP1 (lanes 4, 6, and 8) in a time-dependent manner." (PMID 24489926, 2014). "However, the molecular mechanism of PCBP1 anti-PPV infection remains unclear." (PMID 38742903, 2024). "We also detected decreasing trend of PCBP1 and PCBP2 protein levels with increase in multiplicity of infection (MOI = 1:1, 1:5, 1:10, and 1:20; 2 h) and simultaneous appearances of faster migratory band(s)." (PMID 36309090, 2022). "We observed that the levels of PCBP1 in H7N9-infected A549 cells were down-regulated at 24h and 48h as compared to the H1N1pdm09 infection, which inhibited cell cycle and induced apoptosis." (PMID 27223893, 2016). "Over-expressing PCBP1 reduced the induction of the luciferase expression from two viral late gene promoters (ORF26 and M9 promoters) upon infection." (PMID 22028648, 2011). "However, using receiver operating characteristic curves, we identified four to 48 candidate biomarkers of infection depending on the pathogen, including seven overlapping biomarkers (DSG2, PCBP1, MGAM, APOA4, DPEP1, GOT1, and IGFALS)." (PMID 38193073, 2023). "Taken together, these findings imply that Leishmania-induced GP63-mediated cleavage of PCBP1 and PCBP2 may help the parasite, particularly in the early stage of infection." (PMID 36309090, 2022). "In 3 independent western blot analyses (P<0.05), as shown in, compared with the H1N1pdm09 infection, the down- or up-regulated proteins of CAPZA1 (33KDa), OAT (49KDa), PCBP1 (37KDa), EIF5A (18KDa), PAFAH1B2 (26KDa) in H7N9 infection were consistent with the 2-D DIGE results." (PMID 27223893, 2016). "However, as hepatocytes typically express RIG-I and MAVS, we cannot rule out the possibility that PCBP1 may also modulate this pathway during infection in vivo." (PMID 35215884, 2022). "Investigation on the regulation of PCBP1 and PCBP2 transcripts after the infection (0–2 h) showed no significant alteration by quantitative PCR analysis in splenocytes and by semiquantitative RT–PCR in J774 cells (0–8 h)." (PMID 36309090, 2022).
neurodegenerative disease (5 papers, 2017 to 2024). A disorder of the central nervous system characterized by gradual and progressive loss of neural tissue and neurologic function. "In this study, we cloned and constitutively overexpressed PCBP-1 in rat PC12 cells (PC12 cell is the common cell line studying neurodegenerative disease include PD)." (PMID 35795237, 2022). "There are limited reports on the role of PCBP1 in neurodegenerative diseases." (PMID 38376022, 2024). "Moreover, KEGG analysis showed that Pcbp1 downregulation in these immune cell lines all enriched the terms of aging‐related neurodegenerative diseases and ferroptosis, which again confirmed the critical role of Pcbp1 in anti‐immunosenescence and iron homeostasis." (PMID 37681451, 2023). "Also, PCBP1 plays a as possible regulator in neurodegenerative disease." (PMID 32536864, 2020).
GI tumors (2 papers, 2020 to 2024). "According to recent researches, upper gastrointestinal (GI) tumors with chromosomal instability are characterized in fragmented genomes and lower GI tumors are enriched in mutations in SOX9 and PCBP1, which reveal the heterogeneity between upper GI tumors and lower GI tumors." (PMID 33552958, 2020). "In addition, some transcription factors, including HDGF, NCL, PCBP1, and PCBP2, were also found to be largely modified by lysine lactylation in all four types of GI tumors, and further confirming the regulation of Kla in gene expression." (PMID 39018247, 2024).
hematologic malignancies (1 paper, 2020). "MiR-7977 in extracellular vesicles has been demonstrated to induce failure of normal hematopoiesis via its target gene poly(rC) binding protein 1 (PCBP1) in hematologic malignancies." (PMID 32328453, 2020).
neurological disorders (1 paper, 2024). "For example, PCBP1 has been reported to interact with HSPB1 mutants as well as other genes causing neurological disorders." (PMID 38376022, 2024). "This is also the direction of our ongoing research: understanding how PCBP1 functions as an iron chaperone and its role in neurological disorders." (PMID 38376022, 2024).
peripheral neuropathies (1 paper, 2017). "We hypothesize that mutant HSPB1 can mediate translational repression by forming an interaction with PCBP1 leading to an alteration in the expression levels of genes important to cause peripheral neuropathies." (PMID 28077174, 2017).
PCBP1 also shares sentences with these, for which no sentence is quoted: lung carcinoma (2 papers); myelodysplastic syndrome (2); rectal cancer (2); amyotrophic lateral sclerosis (1); autoimmune disease (1); Autoimmunity (1); cervical dysplasia (1); depression (1); folate deficiency (1); hereditary peripheral neuropathies (1); injury (1); metastatic cancers (1); metastatic tumor (1); multiple sclerosis (1); myelogenous leukemia (1); neurodevelopmental disorder (1); primary sclerosing cholangitis (1); prostate adenocarcinoma (1); rectum tumors (1); rheumatoid arthritis (1); serous malignant ovarian tumors (1); serous ovarian cancer (1); squamous intraepithelial lesions (1); tuberculosis (1).